MOGAT2 (monoacylglycerol O-acyltransferase 2)
Description:
Involved in glycerolipid synthesis and lipid metabolism. Catalyzes the formation of diacylglycerol, the precursor of triacylglycerol, by transferring the acyl chain of a fatty acyl-CoA to a monoacylglycerol. Plays a central role in absorption of dietary fat in the small intestine by catalyzing the resynthesis of triacylglycerol in enterocytes (By similarity). Has a preference toward monoacylglycerols containing unsaturated fatty acids in an order of C18:3 > C18:2 > C18:1 > C18:0 at sn-2. Able to use 1-monoalkylglycerol (1-MAkG, 1-O-alkylglycerol) as an acyl acceptor for the synthesis of monoalkyl-monoacylglycerol (MAMAG, 1-O-alkyl-3-acylglycerol or 1-O-alkyl-2-acylglycerol) and subsequently, with lower efficiency, may add another acyl chain producing monoalkyl-diacylglycerol (MADAG, 1-O-alkyl-2,3-diacylglycerol). Possesses weak but significant activity with diacylglycerol as substrate, producing triacylglycerol (triacyl-sn-glycerol).
Synonyms: MGAT2; hDC5; DGAT2L5; FLJ22644; DGAT2L5.
Tractability: Small molecule: a high-quality ligand is known. Antibody: UniProt predicts a signal peptide or a membrane-spanning region. PROTAC: a small molecule that binds it is known.
Target class: Enzyme; Transferase
Gene: Protein-coding gene on chromosome 11 (75,717,838 to 75,732,963, forward strand). Ensembl gene ENSG00000166391.
Subcellular location: Endoplasmic reticulum membrane; Cytoplasm, perinuclear region
Pathways (Reactome):
Metabolism: Triglyceride biosynthesis
Gene Ontology:
Molecular function: 2-acylglycerol O-acyltransferase activity; acetyltransferase activity; acyltransferase activity, transferring groups other than amino-acyl groups; diacylglycerol O-acyltransferase activity
Biological process: monoacylglycerol biosynthetic process; diacylglycerol biosynthetic process; triglyceride biosynthetic process
Cellular component: endoplasmic reticulum; perinuclear endoplasmic reticulum membrane; endoplasmic reticulum membrane; perinuclear region of cytoplasm
Genetic constraint (gnomAD): Loss-of-function variants: 28 observed, 36.62 expected, observed/expected ratio (o/e) 0.76, 90% interval 0.57 to 1.05. The upper end of that interval is the gene's LOEUF score, 1.05, which puts it in group 4 of 6, group 1 being the genes least tolerant of losing a copy. Missense variants: 436 observed, 455.45 expected, observed/expected ratio (o/e) 0.96, 90% interval 0.88 to 1.04. Synonymous variants: 163 observed, 178.67 expected, observed/expected ratio (o/e) 0.91, 90% interval 0.8 to 1.04.
Homologues: Orthologues: chimpanzee MOGAT2 (99% identical), macaque MOGAT2 (98% identical), rabbit MOGAT2 (85% identical), dog MOGAT2 (82% identical), mouse Mogat2 (81% identical), pig MOGAT2 (81% identical), rat Mogat2 (81% identical), guinea pig MOGAT2 (68% identical), tropical clawed frog mogat2.2 (63% identical), zebrafish mogat2 (49% identical), Caenorhabditis elegans dgtr-1 (45% identical), Caenorhabditis elegans dgat-2 (44% identical), and 5 more. Paralogues in human: MOGAT1 (53% identical), DGAT2 (46% identical), MOGAT3 (46% identical), DGAT2L6 (43% identical), AWAT1 (43% identical), AWAT2 (42% identical).
Diseases named in the same sentence as MOGAT2 in open-access papers:
MOGAT2 is named in the same sentence as 20 diseases in open-access papers, as found by Europe PMC text mining. Sharing a sentence is not in itself a finding about the gene and the disease. The quoted sentences say what the papers report.
Obesity (11 papers, 2010 to 2025). Accumulation of substantial excess body fat. "MOGAT2, an important membrane-bound acyltransferase involved in the synthesis of DG and triglycerides, is associated with hyperlipidemia, obesity, and insulin resistance." (PMID 40860874, 2025). "MOGAT2 deficiency results in increased energy expenditure and the suppression of weight gain in a genetic mouse model of obesity." (PMID 36290165, 2022). "MOGAT2 was found to be associated with triacylglycerol synthesis and has a role in diet-induced obesity." (PMID 20122255, 2010). "The dual effects of MOGAT2 inhibitors on lowering triglycerides and causing weight loss has great potential in treating MASLD/MASH, as obesity is a major risk factor in driving the progression of MASLD/MASH." (PMID 39505262, 2024). "MOGAT2 was identified as the lowest expressed gene (log2-fold change −4.72) in pigs of the CO group present in the “triacylglycerol biosynthesis in obesity and diabetes mellitus type II”." (PMID 36816031, 2023). "Transgenic and pharmacological studies in mice have demonstrated the beneficial effects of MOGAT2 inhibition as a therapy for several metabolic diseases, including obesity and insulin resistance." (PMID 36834823, 2023). "Given its role in the absorption of dietary fat, MOGAT2 has been established as an important driver of obesity in humans." (PMID 36290165, 2022). "Diet-induced obesity was associated with an increase in circulating glycerol levels as well as with an upregulation of AQP7 in BAT, which was strongly associated with the increase in the lipogenic factors Pparg2, Mogat2 and Dgat1." (PMID 36834823, 2023). "Mice lacking MOGAT2 expression are reportedly resistant to obesity and high-fat diet-associated metabolic disorders." (PMID 36290165, 2022). "Thus, MOGAT2 plays a role in diet-induced obesity and metabolic syndrome." (PMID 39459569, 2024). "Monoacylglycerol O-acyltransferase 2 (MGAT2) catalyzes the synthesis of diacylglycerol (DG), a triacylglycerol precursor and potential peripheral target for novel anti-obesity therapeutics." (PMID 26938273, 2016). "Due to their involvement in TG re-synthesis and secretion, it is believed that MOGAT2 and 3, but also DGAT1 are potential therapeutic drug targets for treating diet-induced dyslipidemia and obesity, whereas an activation of PPARα was suggested as the initial regulator." (PMID 23241455, 2012).
Hepatic steatosis (4 papers, 2016 to 2023). Steatosis is a term used to denote lipid accumulation within hepatocytes. "Intestine-specific deletion of Mogat2 in mice was also protective against hepatic steatosis while expression of Mogat2 only in the small intestine of global Mogat2-deficicent mice caused accumulation of TG in the liver." (PMID 35322811, 2022). "Moreover, obese animals showed higher (P < 0.05) transcript levels of the lipogenic genes Pparg, Srebf1, Mogat2 and Dgat1 as well as a moderate-to-severe hepatic steatosis evidenced by the staining of the lipid droplet-coating protein adipophilin in liver sections." (PMID 28008992, 2016). "And these results indicated that AR could modulate ether lipid metabolism to ameliorate CCl4-induced hepatic steatosis and fibrosis by regulating PCYT1A and MOGAT2." (PMID 31467589, 2019).
steatosis (4 papers, 2016 to 2023). Increased lipid within the cytoplasm of cells. "Sleeve gastrectomy did not change BAT weight, but improved BAT morphology and function, as shown by the reduction in brown adipocyte hypertrophy and steatosis, together with the repression of the transcription of the lipogenic genes Pparg2, Mogat2 and Dgat1." (PMID 36834823, 2023). "DIO promoted BAT whitening, evidenced by increased BAT hypertrophy, steatosis and upregulation of the lipogenic factors Pparg2, Mogat2 and Dgat1." (PMID 36834823, 2023). "Importantly, both guanylin and uroguanylin decreased basal and palmitate-induced steatosis and downregulated factors involved in lipogenesis (Srebf1, Mogat2 and Dgat1)." (PMID 37274331, 2023). "Accordingly, sleeve-gastrectomized rats exhibited a tendency towards a downregulation in hepatic Pparg (P = 0.084) and Srebf1 (P = 0.153) transcription factors as well as lower (P < 0.05) mRNA levels of Mogat2 and Dgat1 and mild steatosis evidenced by adipophilin staining." (PMID 28008992, 2016). "ANGPTL8 reduced the steatosis (p < 0.05) and mRNA expression levels of PPARG2, SREBF1, MOGAT2 and DGAT1 lipogenic genes of palmitate-treated hepatocytes." (PMID 34884755, 2021). "Interestingly, ANGPTL8 inhibited steatosis and expression of lipogenic factors (PPARG2, SREBF1, MOGAT2 and DGAT1) in palmitate-treated human hepatocytes." (PMID 34884755, 2021).
diabetes (3 papers, 2016 to 2024). "A recent genome-wide human exome ChIP study did uncover a genetic variant in MOGAT2 (rs499972) linked to the accumulation of diabetes-associated metabolites." (PMID 39505262, 2024). "We identified a total of 16 loci associated with diabetes-related metabolite traits, including one novel association between rs499974 (MOGAT2) and a diacyl-phosphatidylcholine ratio (PC aa C40:5/PC aa C38:5)." (PMID 28729637, 2017).
type 2 diabetes (3 papers, 2017 to 2023). "Besides, rs499974 of MOGAT2 might be relevant for the risk of type 2 diabetes through single variant analyses." (PMID 32256214, 2020). "In summary, we identified a novel metabolite locus (MOGAT2) in single variant analyses and four genes (GFRAL, BIN1, TFRC, OR51Q1) within gene-based tests and could show that two previously known mGWAS loci (FADS1 and REV3L) might be relevant for the risk of type 2 diabetes." (PMID 28729637, 2017).
bladder cancer (1 paper, 2020). "Among these identified genes, 5 genes (CALD1, HOXB3, HOXB6, MOGAT2, and TNC) have been reported to be associated with the development or prognosis of bladder cancer, indicating that the results in our study are consistent with previous publications in bladder cancer." (PMID 33204728, 2020).
breast carcinoma (1 paper, 2017). "Of note, the diminished expression of putative hub genes such as CDKN2B, CNNM4, LRRC19, and MOGAT2 might be the result of inactivation of genes through DNA methylation as their methylation was identified in colorectal, gastric, and breast cancers as well as in leukaemia." (PMID 29088818, 2017).
colorectal carcinoma (1 paper, 2024). A malignant epithelial neoplasm that arises from the colon or rectum and invades through the muscularis mucosa into the submucosa. "For instance, previous research has shown that MOGAT2 deficiency enhances colorectal carcinoma growth by activating the NF-κB pathway." (PMID 39478862, 2024).
inflammatory breast carcinoma (1 paper, 2020). An advanced, invasive breast adenocarcinoma characterized by the presence of distinct changes in the overlying skin. "Moreover, MOGAT2 were identified as a differentially methylated gene in inflammatory breast cancer." (PMID 32256214, 2020).
lung carcinoma (1 paper, 2024). "This might suggest that MOGAT2 deficiency could increase energy to promote lung cancer growth, while this need to be further investigated." (PMID 39478862, 2024). "Using CRISPR/Cas9 technology, we knocked down MOGAT2 in lung cancer cells." (PMID 39478862, 2024).
tumor (4 papers, 2021 to 2024). "Further investigation into its molecular mechanisms in LUAD progression is essential, including studying the effects of MOGAT2 overexpression on cell proliferation and MOGAT2 deficiency on modulating the tumor microenvironment in both in vitro and in vivo models." (PMID 39478862, 2024). "MOGAT2 is identified as a potential anti-tumor regulator, offering new insights into its role in LUAD pathogenesis." (PMID 39478862, 2024). "To explore the potential impact of MOGAT2 in the tumor microenvironment, we conducted a Spearman correlation analysis, revealing a positive correlation between MOGAT2 expression and both the immune score and the overall TME score." (PMID 39478862, 2024). "In addition, we further investigated the effects of BMS‐303141 on the expressions of lipid synthesis‐related proteins including SREBF1, MOGAT2, FASN, ACC1, ACS and ACLY in ESCC cells and xenografted tumour tissues by Western blot." (PMID 38426936, 2024). "Next, we observed MOGAT3, but not MOGAT1 or MOGAT2, markedly elevated in resistant PDX tumors and RKO EC-R cells compared with respective sensitive tumor cells." (PMID 39436710, 2024).
cancer (1 paper, 2020). A tumor composed of atypical neoplastic, often pleomorphic cells that invade other tissues. "Beyond that, little is known about the roles of MOGAT2 and C1orf115 in human cancers." (PMID 32256214, 2020).
MOGAT2 also shares sentences with these, for which no sentence is quoted: metabolic syndrome (3 papers); hyperlipidemia (2); Insulin resistance (2); metabolic disease (2); ischemic stroke (1); leukaemia (1); lung adenocarcinoma (1); neuromuscular disease (1).